FOXP4-AS1 (FOXP4 antisense RNA 1)
Gene: Long non-coding RNA gene on chromosome 6 (41,436,972 to 41,562,194, reverse strand). Ensembl gene ENSG00000234753.
Diseases named in the same sentence as FOXP4-AS1 in open-access papers:
FOXP4-AS1 is named in the same sentence as 3 diseases in open-access papers, as found by Europe PMC text mining. Sharing a sentence is not in itself a finding about the gene and the disease. The quoted sentences say what the papers report.
osteosarcoma (1 paper, 2025). A usually aggressive malignant bone-forming mesenchymal neoplasm, predominantly affecting adolescents and young adults. "FOXP4-AS1 (FOXP4-antisense 1) is a long noncoding RNA gene that is implicated in playing a critical role in lung, colon, and osteosarcoma." (PMID 40724930, 2025).
FOXP4-AS1 also shares sentences with these, for which no sentence is quoted: non-small cell lung carcinoma (1 paper); tumor (1).